RUNX2 (RUNX family transcription factor 2)
Diseases named in the same sentence as RUNX2 in open-access papers (continued):
Sharing a sentence is not in itself a finding about the gene and the disease.
osteoporosis (continued). "BM cells from the femurs and tibias of recipient mice injected with SM-EVs (from patients with tryptase >110 ng/ml) or SM-EVs from patients with osteopenia/osteoporosis showed markedly reduced mRNA expression levels of Alp, Runx2, Smad1/5, and to a lesser extent Smad2." (PMID 33953168, 2021). "Therefore, the aim of this study was to examine the correlation between the potential DNA binding sites of RUNX2 and osteoporosis." (PMID 34899595, 2021). "Moreover, using mouse models, significant osteoporosis was observed after agomir-23b injection into the caudal vein, and conversely, overexpression of RUNX2 enforced by combined injection of Ad-RUNX2 was found to soothe the bone defects induced by miR-23b." (PMID 34281266, 2021). "In this study, we found that the rs6086746 may affect the binding of the RUNX2 transcription factor to increase PLCB4 expression, thereby increasing the risk of osteoporosis." (PMID 34899595, 2021). "Ectopic expression of circ_0011269 induced RUNX2 expression and suppressed osteoporosis." (PMID 34490735, 2021). "For instance, lncRNA growth arrest-specific transcript 5 (GAS5) may improve osteoporosis through accelerating MSC osteogenic differentiation via the microRNA (miR)-498/runt-related transcription factor 2 (RUNX2) axis." (PMID 34772438, 2021). "Subsequently, the mRNA expression of OPN, OCN, and Runx2 in BMSCs were verified by qRT-PCR, and the results indicated that their levels in exosomes extracted from osteoporosis patients were lower than those in the control group, which was further demonstrated by western blot." (PMID 34229300, 2021). "For instance, it has been reported that in osteoporosis, upregulated miR-23b, miR-3077-5p, miR-212, and miR-384 inhibit osteogenesis by directly targeting Runx2 gene, while in ONFH, upregulated miR-596 and miR-708 hinder osteogenesis by binding to Smad3 transcripts to suppress Runx2 gene expression." (PMID 32963550, 2020). "This study is the first to report miR-505 could bind to the RUNX2 gene and thus regulate partly the dysfunction of osteoblasts differentiation, which is expected to be targets for the treatment of osteoporosis." (PMID 32293484, 2020). "Intervention using miR-488 to target Runx2 may represent a mechanism-based treatment strategy for osteoporosis." (PMID 33013413, 2020). "According to another study, an lncRNA, growth arrest-specific 5 (GAS5), was also present at a low concentration in osteoporosis patients and could also upregulate Runx2." (PMID 33281877, 2020). "miR-488 / Runx2 represents an association that has so far not been used for the treatment of osteoporosis." (PMID 33013413, 2020). "RUNX2 is a transcription factor that controls osteoblast differentiation by regulating the gene expression of the extracellular matrix protein, and it is one of the genes for the pathogenesis of osteoporosis." (PMID 31096652, 2019). "Also in the bone fractures and postmenopausal osteoporosis inhibiting bone regeneration, Runx2 expression was reduced." (PMID 31015371, 2019). "Moreover, berberine (BBR) has been shown to alleviate osteoporosis, and stimulate bone area formation in calvarial organ culture through its role in stimulating osteoblast differentiation by activating RUNX2 by p38 MAPK35." (PMID 31700003, 2019). "The results suggest that Lnc-AK045490 suppresses β-catenin/TCF1/Runx2 signaling and inhibits osteoblast differentiation and bone formation, providing a novel mechanism of osteogenic differentiation and a potential drug target for osteoporosis." (PMID 31835596, 2019). "However, MSC-based therapy for osteoporosis in CCD patients is difficult due to a reduction in the ability of MSCs to differentiate into osteoblasts resulting from impaired RUNX2 function." (PMID 29357927, 2018). "Runx2 gene expression must be tightly regulated to support skeletal health, although sufficient activity is necessary for adequate osteogenesis because reduced or excessive Runx2 activity may lead to osteoporosis." (PMID 29357927, 2018).
osteoporosis (continued). "circRUNX2 could sponge miR‐203 and enhance RUNX2 expression, thus circRUNX2 prevents osteoporosis and may provide a novel therapeutic strategy for it." (PMID 30324718, 2018). "Thus enhancement of HO-1 expression by costunolide in turn leading to enhanced Runx2 expression ultimately led to prevention of osteoporosis." (PMID 30283334, 2018). "Runt-related transcription factor 2 (RUNX2) haploinsufficiency causes cleidocranial dysplasia (CCD) which is characterized by supernumerary teeth, short stature, clavicular dysplasia, and osteoporosis." (PMID 29357927, 2018). "GCs also can upregulate the expression of PPAR-γ, downregulate the Runx2 to break the dynamic balance between adipogenesis and osteogenesis of BMSCs, and lead to fat tissue accumulation in bone marrow; eventually the degree of osteoporosis was increased." (PMID 26941827, 2016). "Furthermore, miR-135b may inhibit osteogenic differentiation and osteoblast proliferation by targeting RUNX2, thereby contributing to the onset and progression of osteoporosis." (PMID 41530916, 2026). "In summary, our study reveals that RUNX2 phase separation mediates the long‐range interaction between non‐coding susceptibility SNP rs4683184 and target gene XCR1, and then regulates the expression of XCR1 involved in osteoblast differentiation and osteoporosis." (PMID 39704037, 2025). "Thus, this research identifies NIBAN2‐regulated RUNX2 alternative splicing as a potential mechanism of osteoblast differentiation that may present strategies for antagonizing osteoporosis." (PMID 40051391, 2025). "Thus, our research identifies NIBAN2‐regulated RUNX2 alternative splicing as a potential mechanism of osteoblast differentiation that may present strategies for antagonizing osteoporosis." (PMID 40051391, 2025). "Therefore, the miRNA-702-5p/OGN/Runx2 signaling axis may play a role in DOP, and could be diagnostic biomarker and therapeutic target for not only DOP but also other forms of osteoporosis." (PMID 38862780, 2024). "Mechanistically, dysregulation of osteoblasts and osteoclasts induced by abnormal expression of TLR4 is the main molecular mechanism underlying TLR4-mediated osteoporosis, which may be associated with the interactions between TLR4 and NF-κB pathway, proinflammatory effects, ncRNAs, and RUNX2." (PMID 38504994, 2024). "In the present study, BSHX could reduce osteoporosis symptoms in bone through RUNX2 upregulation." (PMID 38019761, 2023). "Tumor necrosis factor-α (TNF-α) is a well-recognized inhibitory factor in BMSC osteogenic differentiation and was shown to induce miR-23b expression, which could lower Runt-related transcription factor 2 (Runx2) and consequently reduce osteogenesis leading to severe osteoporosis in mice." (PMID 32846921, 2020). "CircRUNX2 might prevent osteoporosis through regulating has‐miR‐203 and RUNX2." (PMID 30324718, 2018). "Thus, prevention or reversal of Runx2 acetylation may represent a new therapeutic strategy for suppression of osteoporosis." (PMID 22539994, 2012). "European-focused GWAS have identified key loci for osteoporosis, including WNT signaling (SOST, LRP5) and RUNX2 transcriptional regulation." (PMID 40411668, 2025). "In osteoporosis, TRAF2 is thought to inhibit BMP signaling as TNF-α exposure results in decreased phospho-Smad1, BMPR-IA, and Runx2 levels, while BMPR-IB and BMPR-II levels increase." (PMID 40496246, 2025). "In an alcohol-induced osteoporosis model, ICA upregulated BMP2 and activated Smad signaling, thereby influencing key factors like Osx and Runx2 to promote bone regeneration." (PMID 40872565, 2025). "Several genes identified through GWAS, including TNFRSF11B, LRP5, RUNX2, SP7, SOST, DKKI, and ESR1, strongly impact osteoporosis development." (PMID 40496246, 2025).
osteoporosis (continued). "For example, in a diabetic osteoporosis model, ICA upregulated Runx2 and the OPG/RANKL ratio, improving the imbalance between osteogenesis and adipogenesis, potentially through glycemic control and activation of osteogenic pathways." (PMID 40872565, 2025). "This leads to the upregulation of Runx2 and OPG, ultimately remodeling bone structure and alleviating osteoporosis." (PMID 41003325, 2025). "RT-qPCR revealed that after the downregulation of SFRP5, the mRNA and protein levels of Runx2, ALP, and OPN in the femur and tibia of rats with dexamethasone-induced osteoporosis were significantly increased." (PMID 39606935, 2025). "At the same time, we also found that Irisin treatment significantly increased the expression of osteogenic genes (Runx2, OSX, OCN, OPN, ALP and BMP2) in BMSCs of osteoporosis mice, while SB203580 strongly weakened this function of Irisin." (PMID 38500202, 2024). "The reciprocal regulatory relationship between RUNX2 and AGE-RAGE signaling pathways in osteogenic differentiation, osteoporosis, and smooth muscle cell calcification has also been confirmed by other researchers." (PMID 38885076, 2024). "Suppression of miR-92b-3p expression increased Nox4 and NF-κB levels, decreased Smad7, BMP2, and RUNX-2 genes and protein expression, and inhibited BMSC proliferation and osteoblast differentiation, resulting in worsened osteoporosis." (PMID 37239124, 2023). "In the osteoporosis mouse model, intravenous injection of HAB‐30Kc19α‐RUNX2 results in preferential accumulation in the femur and promotes bone formation while reducing toxicity in the spleen." (PMID 37574255, 2023). "After the generation of osteoporosis model, mice were treated with HAB‐30Kc19α‐RUNX2 via tail vein injection." (PMID 37574255, 2023). "Herein, we successfully developed a therapeutic agent to treat osteoporosis, consisting of polyaspartic acid moieties (HAB) serving as a bone‐targeting ligand and 30Kc19α‐RUNX2 fusion protein as a cell‐penetrable bone‐forming protein complex." (PMID 37574255, 2023). "This study will inspect at the differences in osteoblast/osteoclast ratio, RANKL/OPG ratio, TRAP, RUNX2, Osterix, and VEGF expressions in Wistar rats with DM and osteoporosis." (PMID 35785822, 2023). "AKT has also been reported to affect osteoporosis by upregulating FOXO1 and enhancing the expression of bone turnover markers (ALP, OCN, Runx2, and Col1) and extracellular matrix mineralization." (PMID 38260098, 2023). "In osteoporosis, VSMC can be transformed into osteoblast-like cells, with the induction of markers such as runt-related transcription factor 2 (Runx2), SRY-Box 9 (Sox9), etc.." (PMID 35498045, 2022). "Recently, a report has indicated that circ_0005564 significantly increased the mRNA levels of osteogenic differentiation markers, including RUNX2, OPN, and OCN, and then played energetic roles in osteoporosis." (PMID 35992137, 2022). "The present study determined that expression of osteoblastic markers BMP-2, RUNX2, OSX, ALP, OPN and BSP-1 were significantly decreased in OVX-induced osteoporosis while treating PMT increased those of osteoblastic markers in a dose-dependent manner." (PMID 33841161, 2021). "It was reported that miR-19a-3p expression in osteoporosis patients was decreased and miR-19a-3p overexpression was demonstrated to target HDAC4 and increase the expression of ALP, OCN, and Runx2." (PMID 32846921, 2020). "NM improved proliferation, ALP activity, mineralization, and expression of osteoblast differentiation markers (BMP-2, p-SMAD 1/5/8, RUNX2, Wnt3a, osteocalcin, and COL-1) in an osteoblastic cell line in vitro and in a model of osteoporosis in vivo." (PMID 32013042, 2020). "The present study also demonstrated that vitamin C enhanced the expression of the osteoblast-specific genes, BMP-2, SMAD1/5/8, RUNX2, osteocalcin, and COL-1, in an in vivo model of osteoporosis." (PMID 30818817, 2019).
osteoporosis (continued). "The potent antioxidant effect of CCE alleviated the progress of osteoporosis partly through modulation of RANKL/OPG and RunX2 signals." (PMID 31826180, 2019). "In this study, we found that the expression of miR-10b was positively correlated with bone formation marker genes ALP, RUNX2 and OPN, and negatively correlated with adipogenic markers CEBPα, PPARγ and AP2 in clinical osteoporosis samples." (PMID 30574418, 2018). "Overexpression of circRUNX2 promoted the expression of osteogenic differentiation‐related proteins such as RUNX2, OCN, OPN, BSP, and prevented osteoporosis." (PMID 30324718, 2018). "In our study, we proposed the role of miR-204-5p-SOX11 regulation in aging osteoblasts, and the potential downstream regulation of BMPR1A/Runx2 signaling by SOX11, a signaling pathway involved in osteoporosis and OA." (PMID 29371932, 2017). "As skeletal development or bone formation activity, the markers of osteogenic differentiation of BMSCs, such as RUNX2, COL1a2, and BMPR1B, were decreased in the osteoporosis group." (PMID 27171263, 2016). "In the glucocorticoid-induced osteoporosis rat model, the use of Gastrodin was found to improve osteoporosis status by activating the Nrf2/Keap1 pathway and upregulating the expression of OCN, BMP-2, and RUNX2." (PMID 41282615, 2025). "In osteoporosis, there is a reduction in the acetylation of the H3K9/K14 and H4K12 regions in the regulatory regions of the RUNX2 and OSX genes, and an increase in acetylation at these same sites in the regulatory region of the PPARy2 gene in mesenchymal stem cells (MSCs) derived from bone marrow." (PMID 39997614, 2025). "Gossypol also significantly enhanced medullary and cortical BMD, the expression of Wnt protein, β-catenin, and GSK-3β, as well as the mRNA levels of osteogenesis-related genes, including osteocalcin, Runx2, OPG, and COL1A1, in mice with osteoporosis compared to control mice." (PMID 39606935, 2025). "It is known that key epigenetic changes in osteoporosis affect the regulation of signalling pathways involved in mesenchymal stem cell (MSC) differentiation, including the activity of the transcription factor RUNX2, sclerostin, and DKK1." (PMID 39997614, 2025). "This inhibition leads to the downregulation of T-cell-specific transcription factor 1 (TCF-1), Runt-related transcription factor 2 (Runx2), alkaline phosphatase (ALP), and osteopontin (OPN), which are downstream osteogenic markers, thereby promoting osteoporosis." (PMID 39606935, 2025). "Consequently, they inhibit osteogenic genes, including Runx2, ALP, and OCN, as well as the osteoclast-suppressing gene OPG, thereby contributing to the progression of osteoporosis." (PMID 39606935, 2025). "Taken together, our findings suggest that FXR plays pivotal roles in osteoblast differentiation by regulating RUNX2 stability and that targeting FXR may be a promising therapeutic approach for osteoporosis." (PMID 39885145, 2025). "A similar effect has been reported for circ-VANGL1, whose decreased expression in BMSCs isolated from osteoporosis patients was related to the negative modulation of RUNX2 and osteoporosis promotion." (PMID 38164139, 2024). "In addition to the TLR4/NF-κB pathway, proinflammatory effects, ncRNAs, and RUNX2, some other potential molecular mechanisms are also proposed for TLR4-mediated osteoporosis." (PMID 38504994, 2024). "However, the BMP-2/Smad/Runx2 signalling cascade activity was reduced in the bone tissues of OVX rats, exacerbating osteoporosis." (PMID 37239124, 2023). "We showed that the expression of ANAPC1 is reduced in the bone and muscle tissue of osteoporosis patients and that ANAPC1 influences the processes of osteogenic differentiation of the human osteosarcoma cell line by downregulating RUNX2 during osteogenic differentiation." (PMID 37629076, 2023).
osteoporosis (continued). "Overexpression of FTO in BMSC promoted the progression of osteoporosis by inhibiting osteogenic differentiation through demethylation of Runx2 gene, and inhibition of FTO in ovariectomized mice showed increased bone formation, partially alleviating OVX-induced osteoporosis." (PMID 38020896, 2023). "Furthermore, decitabine promotes osteogenic differentiation in a murine model of osteoporosis by decreasing the methylation levels of osteogenic genes, such as RUNX2 (Runt related transcription factor 2)." (PMID 37626900, 2023). "Furthermore, we analyzed some osteoporosis-related genes, such as ALP, OPG, RUNX2, RANKL and TRAF-6." (PMID 36835176, 2023). "Runx1 maintained adult bone homeostasis and bone differentiation though upregulating Bmp7/Alk3/Smad1/5/8/Runx2/ATF4 and WNT/β-Catenin signaling pathways, suggesting that targeting Runx1 might be a novel therapeutics for osteoporosis." (PMID 37156809, 2023). "After transfection with miR‐196a mimic, the MSCs (isolated from osteoporosis mice) displayed significantly elevated ALP vitality, increased bone formation ability and higher expression levels of osteogenesis‐related factors, including ALP, RUNX2 and OPN." (PMID 34918401, 2022). "Patients with osteoporosis often have lower OCN and RUNX2 compared to healthy people." (PMID 35529937, 2022). "Anti-Osteoporosis Decoction (AOD) and Yougui Pill treatment effectively inhibits osteoporosis and reduces the broken trabecular bones, increases the level of BMD, ALP levels, accompanied by the increased expressions of BMP2, Runx2, Collagen I and OPN." (PMID 36387862, 2022). "It is speculated that QGY may inhibit autophagy, activate the AKT/mTOR pathway, reduce the expression of CKIP-1 and RANKL, and promote the expression of RUNX2 and OPG, thereby improving osteoporosis." (PMID 35073518, 2022). "Western blot analysis showed reduced protein levels of Runx2, osterix, LC3II/I and elevated P62 protein level in osteoporosis mice injected with miR‐15b antagomir, while the results were opposite in osteoporosis mice injected with miR‐15b antagomir and expression vectors containing KDM6B (P < .05)." (PMID 33434305, 2021). "Therefore, we examined the mRNA levels of RUNX2 and PLCB4 in whole blood extracted from 5 osteopenia patients, 4 osteoporosis patients and 4 controls." (PMID 34899595, 2021). "In addition, BMMSCs displayed significantly lower ALP activity and fewer mineralized nodules, as well as down‐regulated RUNX2, OXS and OCN after post‐menopausal osteoporosis." (PMID 32198976, 2020). "In addition, taurine increased the expression levels of BMP-2, Wnt3a, SMAD1/5/8, RUNX2, and COL-1 in the in vivo osteoporosis model and stimulated the p-Akt, p-p38, p-JNK, and p-ERK signaling pathways." (PMID 31970094, 2019). "Similarly, our results showed that RunX2 and OCN expression levels were lower in femur tissue from DEX-induced osteoporosis rats." (PMID 31826180, 2019). "We collected 30 clinical samples from osteoporosis patients of different ages and analyzed the correlation between the expression of miR-10b and the bone formation marker genes ALP, OPN and RUNX2, and the correlation between miR-10b and adipocyte formation markers CEBPα, PPARγ and AP2." (PMID 30574418, 2018). "Furthermore, these Ca extracts increased the expression levels of BMP-2, Wnt3a, SMAD5, RUNX2, osteocalcin and COL-1 in an in vivo model of osteoporosis, while they decreased TRAP, cathepsin K and RANK expression levels." (PMID 28513557, 2017). "By interrogating the microarray data from osteoporosis patients, we revealed an upregulation of the epigenetic modifying protein lysine (K)-specific demethylase 5A (KDM5A) and decreased Runt-related transcription factor 2 (RUNX2) expression." (PMID 27512956, 2016). "Notably, lower RUNX2 exon 6‐inclusive ratio in osteoporosis patients was attributed lower level of RUNX2FL, rather than elevated level of RUNX2Δ6." (PMID 40051391, 2025).